CHI3L1 (chitinase 3 like 1)
Diseases named in the same sentence as CHI3L1 in open-access papers (continued):
Sharing a sentence is not in itself a finding about the gene and the disease.
breast cancer (113 papers, 1999 to 2026). A primary or metastatic malignant neoplasm involving the breast. "Expression of CHI3L2, which is similar in structure to CHI3L1, is detected in glioma cells and tumor-associated macrophages (TAMs) in glioma and breast cancer." (PMID 39557919, 2024). "Analysis of GEO databases has indicated that CHI3L1 is associated with a worse prognosis in breast cancer patients." (PMID 35309358, 2022). "Tumor‐recruited M2 macrophages can secret CHI3L1 to promote the metastasis of gastric cancer and breast cancer, and elevated serum levels of CHI3L1 glycoprotein are associated with poor prognosis in patients with metastatic breast cancer." (PMID 33626234, 2021). "More recently, it was reported that cancer-associated fibroblast-derived CHI3L1 enhances the migration and growth of breast cancer by suppressing the T cell population and IFN-γ and TNF-α expression." (PMID 33664231, 2021). "We demonstrated that human ER+ breast cancer cells with a point mutation in the ligand binding domain of ESR1 (encodes ER) had increased expression of CHI3L1 when compared to those with wild type ESR1." (PMID 34832904, 2021). "The expression of Chi3l1 was significantly increased by melanoma tumor cell challenge and Chi3l1 deficiency reduced lung metastasis of melanoma or breast cancer cells." (PMID 29403003, 2018). "Although tumor cells and activated splenic macrophages express CHI3L1, a molecule associated with poor prognosis in breast cancer patients, few studies have analyzed CHI3L1 expression by alveolar and interstitial macrophages in tumor bearing models." (PMID 24399973, 2013). "Elevated levels of chitinase-3-like-1 (CHI3L1) are associated with poor prognosis, shorter recurrence-free intervals and low survival in breast cancer patients." (PMID 24399973, 2013). "Increased levels of CHI3L1 in the sera of breast cancer patients are associated with poor prognosis." (PMID 24399973, 2013). "CHI3L1 encodes a 40-kD mammalian glycoprotein, and increased CHI3L1 levels were reported to be correlated with poor prognosis in several types of cancer including breast cancer." (PMID 32631391, 2020). "It was recently reported that CAF-derived Chitinase 3-like 1, which is implicated in inflammatory disorders, contributed to tumour growth in breast cancer and this contribution is accompanied by a high infiltration of M2-polarized macrophages and TH2 type immune responses." (PMID 30816272, 2019). "Our data indicated that the CHI3L1 levels in the sera of patients with cancer were significantly elevated compared with those of healthy donors, which suggests its potential as a diagnostic marker of gastric and breast cancers." (PMID 28143526, 2017). "The secreted cytokine chitinase-3-like 1 (CHI3L1) is frequently overexpressed in breast cancer samples and promotes an immunosuppressed tumor microenvironment." (PMID 41632530, 2026). "To investigate its role in breast cancer metastasis, we generated an inducible genetically engineered mouse model that overexpresses CHI3L1 in the mammary epithelium." (PMID 41632530, 2026). "Ectopic expression of CHI3L1 in the polyomavirus middle T (PyMT) mouse model of breast cancer suppressed antitumor immune responses, accelerated mammary tumor onset, and enhanced lung metastasis." (PMID 41632530, 2026). "Another study implanted breast cancer stem cells (BCSCs-231) into the mammary fat pad of mice and administered anti-CHI3L1 antibody, which suppressed tumor growth." (PMID 40643503, 2025). "In a model using 4T1 breast cancer cells, CHI3L1 expression was upregulated during the premetastatic phase." (PMID 40643503, 2025). "Tumor-recruited M2 macrophages drive metastasis in both GC and breast cancer via the secretion of chitinase 3-like 1 (CHI3L1), initiating the mitogen-activated protein kinase (MAPK) signaling pathway." (PMID 37597212, 2024).
breast cancer (continued). "Elevated levels of the CHI3L1 protein have been detected in the serum of cancer patients, including those with gliomas, colorectal, lung and breast cancer as well as leukemia." (PMID 39557919, 2024). "CHI3L1 is one of the best known chitinase proteins and is currently known to have a pro-tumor and pro-angiogenic effect in many types of cancer, including breast cancer." (PMID 39557919, 2024). "The study demonstrates that the CHI3L1 protein secreted by tumor-recruiting M2 macrophages promotes metastasis in gastric and breast cancers." (PMID 38034950, 2023). "This is similar to results obtained by other researchers, specifically results indicating that, in breast cancer progression, CHI3L1 is mainly expressed by M2 macrophages and promotes further metastasis and spread of breast cancer through M2 macrophages." (PMID 38003338, 2023). "A study on shrimp found that the anti-viral miRNA mja-miR-35 in the shrimp body can target the CHI3L1 gene in M2 macrophages in breast cancer mice in a cross-phylum manner, thereby inhibiting breast cancer metastasis and achieving an anti-tumor effect." (PMID 38003338, 2023). "Chitinase-3-llke protein 1 (CHI3L1, YKL-40) was first discovered in mouse breast cancer cells and was named breast regression protein 39 (BRP-39)." (PMID 37215572, 2023). "Ablation of Chi3l1 in the polyoma virus middle T model of breast cancer generated an immune response against tumours and postponed the onset of mammary tumours." (PMID 38203218, 2023). "In breast cancer progression, serum CHI3L1 levels are closely related to the degree of malignancy of breast cancer, and TAMs also play an important role." (PMID 38003338, 2023). "A study has shown that when fibroblast CHI3L1 expression is knocked down in an orthotopic mouse model of breast cancer, the level of activated (α-SMA–expressing) fibroblasts drops." (PMID 37685578, 2023). "An increase in CHI3L1 is observed in malignant tumors, such as lung cancer, breast cancer, and melanoma, inflammation, rheumatoid arthritis, and osteoarthritis, as well as other conditions such as pyroclastic meningitis and community pneumonia 20, 25, 28-36." (PMID 37215572, 2023). "To further verify that TN-BCSCs were involved in the immune escape of tumors via CHI3L1, we constructed an in situ transplantation model of breast cancer in mice with a humanized immune system using EGFP-labeled MDA-MB-231 and BCSCs-231." (PMID 37838657, 2023). "Chitinase 3-like protein 1 (CHI3L1, a glycoprotein highly expressed in solid tumors) secreted by macrophages has been shown to enhance breast cancer cell invasion, migration and adhesion." (PMID 35309358, 2022). "M2 macrophages can promote the metastasis of breast cancer cells in vitro and in vivo by secreting chitinase 3-like protein 1 (CHI3L1), which interacts with interleukin-13 receptor α2 chain (IL-13Rα2) molecules on the plasma membrane of cancer cells." (PMID 36291773, 2022). "In breast cancer, CAFs over-express chitinase-3-like-1 (Chi3L1), a secreted glycoprotein, involved in macrophage recruitment and M2 polarization." (PMID 35814444, 2022). "Further, blockade of astrocyte secreted CHI3L1 increased the survival of mice harboring cortical breast cancer metastases." (PMID 34832904, 2021). "ChI3L1 is highly expressed in CAFs isolated from mouse mammary tumors and in the stroma of human breast carcinoma." (PMID 34681633, 2021). "Tumor-recruited M2 macrophages promote metastasis of gastric cancer and breast cancer by secreting CHI3L1 protein." (PMID 34517345, 2021). "Treatment of macrophages with CHI3L1 increased pro-tumor M2 polarization genes and enhanced the infiltration of immune suppressive T cells into primary mammary tumors." (PMID 34832904, 2021). "In primary breast cancers, elevated levels of tumor and serum CHI3L1 were correlated with poor differentiation, mesenchymal markers, tumor grade and a shorter relapse-free survival." (PMID 34832904, 2021).
breast cancer (continued). "For example, CHI3L1 is secreted by fibroblasts and reshapes the breast cancer microenvironment by promoting the enrichment of M2 macrophages." (PMID 33028341, 2020). "The risk of developing breast cancer due to these mutations was elevated in women who also carry RANKL (rs9533156), OPG (rs2073617), and CHI3L1 (rs4950928)." (PMID 33659210, 2020). "It was also reported that CHI3L1 expression is positively correlated with Her-2/new-enriched and basal-like breast cancer, but the mechanism behind the expression increase was not established." (PMID 32631391, 2020). "Targeting of CAF-derived Chi3L1 had a similar effect in another transplantable model of breast cancer, and resulted in enhanced infiltration of CD8+ T cells and a shift in the tumor cytokine profile toward a Th1-type phenotype." (PMID 31428105, 2019). "Current literature on CHI3L1 in the mammary gland focuses on its role during breast cancer development." (PMID 29892291, 2018). "More recently, it was reported that Chi3l1 by fibroblast enhances migration and growth of breast cancer, and knockdown of Chi3l1 by shRNA increases T cell population and IFNy, TNFα expression." (PMID 29403003, 2018). "Our study showed that shrimp mja-miR-35 inhibited virus infection of shrimp by targeting virus genes (wsv147, wsv279, wsv309, and wsv361) and took an antitumor effect of human breast cancer by targeting CHI3L1, an oncogenic gene in macrophages." (PMID 30258444, 2018). "Our previous study revealed that M2 macrophage-secreted CHI3L1 protein promoted breast cancer metastasis." (PMID 30258444, 2018). "Chi3l1 was discovered in mouse breast cancer cells and has been studied regarding tumors and inflammatory diseases." (PMID 29403003, 2018). "Intraperitoneal administration of chitin particles to mammary tumor-bearing mice has been demonstrated to significantly reduce local CHI3L1 levels." (PMID 29892291, 2018). "Our previous study reveals that M2 macrophage-secreted CHI3L1 protein promotes the metastasis of gastric and breast cancer cells by interacting with interleukin-13 receptor α2 chain (IL-13Rα2) molecules on the plasma membranes of cancer cells." (PMID 30258444, 2018). "Collectively, these data indicated that CHI3L1 protein promoted in vivo breast cancer metastasis by activating the IL-13Rα2 receptor and subsequently, the MAPK pathway." (PMID 28143526, 2017). "Based on examination of the Oncomine and the Gene Expression Omnibus (GEO) databases, high levels of CHI3L1 expression in human tissues correlated with the progression of both gastric cancer and breast cancer." (PMID 28143526, 2017). "The findings of this study revealed that CHI3L1 specifically bound to the interleukin (IL)-13 receptor α2 chain (IL-13Rα2) of gastric and breast cancer cells, thus promoting cancer metastasis." (PMID 28143526, 2017). "The results of this study indicated that the level of CHI3L1 protein in the sera of patients with gastric or breast cancer was significantly elevated compared with those of healthy donors." (PMID 28143526, 2017). "The M2-secreted chitinase 3-like protein 1 (CHI3L1) promoted the metastasis of gastric and breast cancer cells by triggering the mitogen-activated protein kinase (MAPK) signaling pathway." (PMID 28143526, 2017). "The results showed that gastric and breast cancer cell adhesion to fibronectin was significantly increased by treatment with CHI3L1 protein, indicating that CHI3L1 played a positive role in cancer cell adhesion." (PMID 28143526, 2017). "M2 macrophage-secreted CHI3L1 promoted the metastasis of gastric and breast cancer cells in vitro and in vivo." (PMID 28143526, 2017). "Our previous study indicated that M2 macrophages-secreted CHI3L1 (chitinase 3-like protein 1) protein specifically bound to the interleukin (IL)-13 receptor α2 chain (IL-13Rα2) of gastric and breast cancer cells, thus promoting cancer metastasis." (PMID 28804688, 2017).
breast cancer (continued). "We show here that CHI3L1 levels are increased in both the “pre-metastatic” lung and “metastatic” lung of mammary tumor-bearing mice." (PMID 24399973, 2013). "We have previously reported higher circulating levels of CHI3L1 in 4T1 mammary tumor-bearing mice compared with normal mice." (PMID 24399973, 2013). "We therefore determined if CHI3L1 expression is specifically altered in lung epithelial cells isolated from mammary tumor bearers at 2 weeks post-inoculation, compared to those from control mice." (PMID 24399973, 2013). "Since it is known that breast tumor cells metastasize to the lung, we determined if CHI3L1 expression is specifically altered in lungs of mammary tumor bearers compared to control mice." (PMID 24399973, 2013). "We found that expression of CHI3L1 is upregulated in lung epithelial cells, as well as in alveolar and interstitial macrophages of mammary tumor-bearing mice." (PMID 24399973, 2013). "In this study, we explored if in vivo administration of chitin microparticles has an effect on the expression of CHI3L1 and pro-angiogenic molecules in the lungs of mammary tumor-bearing mice." (PMID 24399973, 2013). "Intraperitoneal treatment of mammary tumor bearers with chitin microparticles, a substrate for CHI3L1, results in decreased tumor growth and pulmonary metastasis." (PMID 24399973, 2013). "We have previously shown that CHI3L1 is expressed at higher levels in splenic macrophages of mammary tumor-bearing mice." (PMID 24399973, 2013). "We used an in vivo mouse mammary tumor model mimicking CHI3L1 expression in breast cancer patients to examine the role of CHI3L1 and CHI3L1-induced angiogenic molecules in the pulmonary microenvironment during the emergence of metastasis." (PMID 24399973, 2013). "We also found that interstitial and alveloar macrophages from chitin-treated mammary tumor bearers exhibited reduced expression of CHI3L1, and these same pro-angiogenic molecules, at 5 weeks post-tumor cell inoculation." (PMID 24399973, 2013). "Interstitial macrophages from mammary tumor-bearing mice secrete CHI3L1 and these levels were further increased by stimulation with LPS as determined by ELISA." (PMID 24399973, 2013). "Chi3L1 (synonym: BRP-39) and the human homologue YKL-40, is a protein originally identified in mouse breast cancer cells, which has been associated with a range of chronic inflammatory and allergic conditions and wound healing." (PMID 22081431, 2012). "Chi3l1 is a biomarker of aggressiveness and breast cancer stage." (PMID 40391215, 2025). "CHI3L1 decreased the expression of E-cadherin, which leads to a reduction in cell adhesion and may promote cell migration in breast cancer cells." (PMID 39399677, 2024). "The induction of CHI3L1 expression could affect tumor-related immune responses and promote metastasis in breast cancer." (PMID 37838657, 2023). "Furthermore, we constructed a breast cancer in situ transplantation model using MDA-MB-453 (EGFP marker) to verify the Role of CHI3L1/MAF in promoting TNBC stemness and participating in immunosuppression by exogenously administering hrCHI3L1 or/and sh-MAF-1." (PMID 37838657, 2023). "M2 macrophages also secrete chitinase-3-like protein 1 (CHI3L1), which could promote gastric and breast cancer metastasis by the initiation of the mitogen-activated protein kinase (MAPK) signaling pathway." (PMID 37509382, 2023). "As previously reported, CHI3L1 could induce tumor immune escape in breast cancer by acting on the cytotoxic machinery while preventing granule polarization." (PMID 37838657, 2023). "CHI3L1 was originally discovered in mouse breast cancer cells." (PMID 36581917, 2022). "Recent studies have suggested that CHI3L1 may be a therapeutic target in a broad range of conditions, including COVID-19, bone metabolism, and breast cancer." (PMID 36560606, 2022). "CHI3L1 also plays a key role in inducing immunosuppression and metastasis in breast cancer." (PMID 33937022, 2021).
breast cancer (continued). "Thus, fibroblast-derived ChI3L1 facilitates tumor progression by remodeling the tumor immune microenvironment in breast cancer." (PMID 34681633, 2021). "The expression of chitinase 3-like 1 (Chi3L1) is upregulated in MAFs, and its inhibition can decrease lung metastases in a breast cancer model, suggesting that MAF-derived Chi3L1 may play a role in the metastatic microenvironment." (PMID 34112258, 2021). "CHI3L1 secreted from M2 macrophage promotes breast cancer cell metastasis in vitro and in vivo." (PMID 34722557, 2021). "Similarly, one study shows that M2 macrophages are enriched in gastric and breast cancer tissues and promote metastasis of cancer cells mediated by CHI3L1 protein." (PMID 33330451, 2020). "In addition, an earlier study demonstrated that M2 macrophage promotes the invasiveness of gastric and breast cancer cells by producing chitinase 3-like protein 1 (CHI3L1)." (PMID 31300030, 2019). "The results showed that the mja-miR-35 expression in M2 macrophages significantly inhibited breast cancer cell migration, indicating that mja-miR-35 could suppress breast cancer metastasis by targeting CHI3L1 gene." (PMID 30258444, 2018). "This immunomodulation concept was adapted from a recent breast cancer report that also could lower local CHI3L1 levels, albeit through the intraperitoneal administration of chitin particles in mammary tumor-bearing mice." (PMID 29892291, 2018). "Our study revealed a novel aspect of macrophages with respect to cancer metastasis and showed that CHI3L1 could be a marker of metastatic gastric and breast cancer in patients." (PMID 28143526, 2017). "The findings revealed that the addition of anti-CHI3L1 led to a significant decrease of gastric and breast cancer cell migration in the presence of isolated M2 macrophages compared with the controls, indicating that CHI3L1 played a key role in cancer cell migration." (PMID 28143526, 2017). "We have previously shown that splenic myeloid cells from mammary tumor-bearing mice express CHI3L1." (PMID 24399973, 2013). "In comparing the different cell types present in the lung, i.e., epithelial cells and macrophages, we found that both interstitial and alveolar macrophages from 2 week mammary tumor-bearing mice express much higher levels of CHI3L1 compared to epithelial cells." (PMID 24399973, 2013). "In this study, we determined the expression of CHI3L1 in bronchoalveolar lavage macrophages and interstitial macrophages in regulating angiogenesis that could support the growth of newly immigrant mammary tumor cells into the lung." (PMID 24399973, 2013). "Using mouse mammary tumor models, we have previously shown that during neoplastic progression both the mammary tumor cells and splenic macrophages from tumor-bearing mice express higher levels of CHI3L1 compared to normal control mice." (PMID 24399973, 2013). "Thus, in this study we tested the role of CHI3L1 expression by bronchoalveolar and interstitial macrophages in regulating angiogenesis to promote the growth of new mammary tumor cells in the lung." (PMID 24399973, 2013). "CD11b+Ly6C+ cells from mammary tumor bearers express higher levels of CHI3L1 compared to normals." (PMID 24399973, 2013). "Immunofluorescent analysis of CHI3L1 in paraformaldehyde fixed cells with polyclonal antibodies to CHI3L1 indicated that the protein was localized diffusely in cytoplasm of 293 cells stably expressing CHI3L1, corresponding to the localization of CHI3L1 protein in breast cancer cells." (PMID 23675241, 2011). "CHI3L1, as a protein involved in immune suppression in breast cancer, is directly correlated with the downregulation of IFN-γ expression in tumor-bearing mice, suggesting that CHI3L1 may participate in inducing pre-Th2-type responses, thereby reducing the production of Th1-type cytokines." (PMID 38003338, 2023). "Thus, the role of CHI3L1 as a mediator of EMT needs to be investigated in breast cancer." (PMID 34832904, 2021).